EZH2 (enhancer of zeste 2 polycomb repressive complex 2 subunit)
Diseases named in the same sentence as EZH2 in open-access papers (continued):
Sharing a sentence is not in itself a finding about the gene and the disease.
diabetic foot (1 paper, 2024). A diabetic foot is a foot that exhibits any pathology that results directly from diabetes mellitus or any long-term (or "chronic") complication of diabetes mellitus. "However, the SIRT1/EZH2 axis has hardly been studied in the study of diabetic foot." (PMID 37985432, 2024).
disc degeneration (1 paper, 2020). "In summary, both EZH2 and NOX4 are involved in natural disc degeneration." (PMID 32025238, 2020). "EZH2 and NOX4 are jointly involved in the regulation of aging of NP cells which provide a new idea for further research on the mechanism of disc degeneration, potential targets for early clinical diagnosis and treatment of IDD." (PMID 32025238, 2020).
dyslipidemia (1 paper, 2016). "Moreover, we found a similar trend of H3K27me3 levels after up/down regulated EZH2 expression, which suggested that H3K27me3 might be a vital mechanism for EZH2 on dyslipidemia of foam cells." (PMID 27936205, 2016).
embryonal tumors (1 paper, 2025). "GPC3 and Ki67 gene expression patterns correlate with EZH2 expression with higher expression in embryonal tumors." (PMID 40766612, 2025).
endocrine cancers (1 paper, 2016). "Histone deacetylase (HDAC) activity is indispensable for EZH2-mediated gene repression, and HDAC inhibitors can induce NOTCH1 expression in some endocrine cancers, indicating the relevance of EZH2 and NOTCH1 and their convergence at HDAC." (PMID 27049834, 2016).
endometrial adenocarcinoma (1 paper, 2023). "Moreover, a recent study indicated that SPRED1 expression was upregulated by knockdown of EZH2 in endometrial adenocarcinoma cells." (PMID 36629984, 2023).
endometrial stromal sarcoma (1 paper, 2023). "Genetic mutations of SUZ12, a PRC2 component supporting EZH2 activation, are highly detected in the endometrial stromal sarcoma with increased stromal proliferation." (PMID 37198149, 2023).
erythroleukemia (1 paper, 2017). Acute erythroid leukemia characterised by the presence of at least 50% erythroid precursors and at least 20% myeloblasts in the bone marrow. "In conclusion, MYCN contributes to the malignant characteristics of erythroleukemia through EZH2-meidated epigenetic repression of p21." (PMID 29022893, 2017). "In summary, MYCN contributes to the malignant characteristics of erythroleukemia through EZH2-mediated repression of p21." (PMID 29022893, 2017). "Hence, we speculated that MYCN/EZH2 axis contributes to the malignant characteristics of erythroleukemia through H3K27me3-mediated epigenetic repression of p21." (PMID 29022893, 2017).
female infertility (1 paper, 2021). Diminished or absent ability of a female to achieve conception. "APCDD1 is involved in adipogenic differentiation, CTDSP2 is a target gene of FOXO and regulates cell cycle progression, EZH2 is an important regulator in the female reproductive tract, MGA4A is involved in embryo lethality and female infertility, and RHOQ regulates mitochondrial function." (PMID 34639162, 2021).
fibroma (1 paper, 2024). A non-metastasizing neoplasm arising from the fibrous tissue. "To evaluate the efficacy of Ezh2 shRNA, we first expressed four different Ezh2 shRNA constructs in gerbil fibroma cells." (PMID 38676810, 2024).
gallbladder adenocarcinoma (1 paper, 2021). A carcinoma that arises from glandular epithelial cells of the gall bladder. "EZH2 is found to be upregulated in GBC tissues in previous study and overexpression of EZH2 is associated with invasion, metastasis, and poor progression of gallbladder adenocarcinoma." (PMID 34789260, 2021).
ganglioglioma (1 paper, 2018). A well differentiated, slow growing neuroepithelial neoplasm composed of neoplastic, mature ganglion cells and neoplastic glial cells. "We include the first report of a case with mixed features of both MVNT and conventional ganglioglioma in support of a potential common origin, and we identified two cases with novel mutations in SUFU and EZH2, although these mutations are of uncertain significance." (PMID 28833756, 2018).
ganglioneuroblastoma (1 paper, 2020). A neuroblastic tumor characterized by the presence of neuroblastic cells, ganglion cells, and a stroma with Schwannian differentiation constituting more than fifty-percent of the tumor volume. "Strikingly, expression of G9a and EZH2 was barely detectable in the more differentiated ganglioneuromas and ganglioneuroblastomas, generally regarded as low risk tumors." (PMID 32537432, 2020).
germinoma (1 paper, 2011). A malignant germ cell tumor arising in the central nervous system. "Although we had access to only a small number of RNA samples from the same tumours analysed for their methylation status, our data did reveal a significant difference between germinomas and YSTs in the level of expression of DNMT3B, but not EZH2 or SUZ12 (data not shown)." (PMID 21712824, 2011).
glaucoma (1 paper, 2021). Increased pressure in the eyeball due to obstruction of the outflow of aqueous humor. "It would be nonetheless interesting to reveal whether EZH2 pathway or other epigenetic modifications occurs during glaucoma or other models of optic neuropathies." (PMID 34502238, 2021).
growth disorders (1 paper, 2023). "In addition, we found three new missense variants in PAPPA2, ADAM12 and EZH2, three genes related to growth disorders in different species including humans." (PMID 38017417, 2023).
Hashimoto thyroiditis (1 paper, 2024). An autoimmune disorder caused by the production of autoantibodies against thyroid tissue. "Herein, we present a rare case of PTC combined with PFL featuring an EZH2 gene mutation, which can be easily overlooked in the context of Hashimoto’s thyroiditis." (PMID 38773600, 2024).
Hepatitis (1 paper, 2018). Inflammation of the liver. "Herein, IFN-γ-induced EZH2 and galectin-9fine-tuned the inflammatory response bysuppressing the immune system in hepatitis." (PMID 29316949, 2018).
hepatocellular adenoma (1 paper, 2012). A benign epithelial neoplasm arising from the hepatocytes. "It would be of interest to examine EZH2 expression in beta-catenin positive hepatocellular adenomas, which have a higher tendency for malignant transformation." (PMID 22809481, 2012). "None of the hepatocellular adenomas (n = 24) reacted with EZH2 antibody." (PMID 22809481, 2012).
Hirschsprung disease (1 paper, 2018). Hirschsprung disease (HSCR) is a congenital intestinal motility disorder that is characterized by signs of intestinal obstruction due to the presence of an aganglionic segment of variable extent in the terminal part of the colon. "It is also possible that Hox genes are epigenetically altered in the ENS of the Ezh2 mutants, since Hox genes has been linked to megacolon phenotypes, and combined mutations in Ret and Hox genes have been previously linked to increased penetrance of Hirschsprung’s disease." (PMID 30169530, 2018).
Hyperkalemia (1 paper, 2020). An abnormally increased potassium concentration in the blood. "Besides the promotion of calcium, LSCC also activates multiple genes that produce hyperkalemia, including EGFR, EZH2." (PMID 33092550, 2020).
Hyperoxaluria (1 paper, 2022). Increased excretion of oxalates in the urine. "Likewise, EZH2 inhibition protects against hyperoxaluria-induced kidney injury by blocking the production of ROS and CaOx crystal deposition reduction." (PMID 35883846, 2022).
hyperplastic polyp (1 paper, 2016). A polyp found mainly in the stomach and colon. "Regarding premalignant lesions, negative EZH2 expression was frequently detected in sessile serrated adenomas/polyps (SSA/Ps) (76%; P < 0.0001) compared with hyperplastic polyps, traditional serrated adenomas, and non-serrated adenomas (25–36%)." (PMID 26871294, 2016).
hypopharyngeal tumors (1 paper, 2024). "Higher EZH2 expression seems to characterize hypopharyngeal tumors when compared to either oral cavity or laryngeal malignancies (percentage of positive cells, control group; oral cavity 60% [IQR: 20–90] or larynx 40% [IQR: 10–80] vs. hypopharynx 80% [IQR: 60–90]; Dunn’s post hoc p < 0.05)." (PMID 38791289, 2024).
influenza (1 paper, 2021). An acute viral infection of the respiratory tract, occurring in isolated cases, in epidemics, or in pandemics; it is caused by serologically different strains of viruses (influenzaviruses) designated A, B, and C, has a 3-day incubation period, and usually lasts for 3 to 10 days. "However, we did not discover any difference in neutrophilic inflammatory responses in the epithelial EZH2‐null animals to either LPS or influenza infection." (PMID 34464475, 2021). "We investigated the role of EZH2 in pulmonary mucosal inflammation, and for this used inflammatory challenge models targeting the lung, including nebulized lipopolysaccharide, (LPS), as well as two pulmonary infectious disease models (influenza A and pneumococcus)." (PMID 34464475, 2021).
intraepithelial neoplasia (1 paper, 2014). A precancerous neoplastic process that affects the squamous, glandular, or transitional cell epithelium without evidence of invasion. "The overexpression of EZH2 may induce hypermethylation of the promoter of the p16 gene, reducing the expression of p16, which is a key step in the multistep cholangiocarcinogenesis from hepatolithiasis to intraepithelial neoplasia." (PMID 25036033, 2014).
Jaundice (1 paper, 2025). Yellow pigmentation of the skin due to bilirubin, which in turn is the result of increased bilirubin concentration in the bloodstream. "Mutations in the EZH2 gene may impair the normal differentiation and function of hepatocytes, leading to disordered bilirubin metabolism and resultant jaundice." (PMID 40922349, 2025).
keloid (1 paper, 2022). An irregularly shaped, elevated mark on the skin caused by deposits of excessive amounts of collagen during wound healing. "Herein, we aim to investigate the role and mechanism of SIRT1/EZH2/RUNX3 in abnormal proliferation of benign keloids." (PMID 36476345, 2022). "Herein, we investigated the mechanism of abnormal proliferation in keloids involving Sirtuin 1(SIRT1)/ Zeste Homolog 2 (EZH2)/ Runt-related transcription factor 3 (RUNX3)." (PMID 36476345, 2022). "The mechanism of cell proliferation involving SIRT1/EZH2/RUNX3 in benign keloids is still unclear." (PMID 36476345, 2022). "However, the expression level of EZH2 in keloid tissues was significantly higher than that in adjacent skin tissues (P < 0.05)." (PMID 36476345, 2022). "In summary, our study shows that SIRT1 could promote proliferation by reducing RUNX3 expression in keloids through deacetylation of EZH2." (PMID 36476345, 2022). "Conclusively, the SIRT1/EZH2/RUNX3 axis may be an important pathway in the regulation of abnormal proliferation in keloids." (PMID 36476345, 2022). "However, the post-translational modification of EZH2 has rarely been reported in keloids." (PMID 36476345, 2022). "SIRT1/EZH2/RUNX3 axis may be important for regulating abnormal proliferation in keloids." (PMID 36476345, 2022). "The expression levels of SIRT1, EZH2 and RUNX3 in keloid specimens and their normal adjacent tissues were detected by Western blot." (PMID 36476345, 2022). "Similar results of SIRT1, EZH2 and RUNX3 were also observed in keloid fibroblasts and normal fibroblasts." (PMID 36476345, 2022). "Considering that RUNX3 may act at tumor suppressor gene in keloids, we analyzed the correlation of SIRT1, EZH2, and RUNX3 expression in keloid tissues and found that there were negative regulatory relationships between SIRT1 and EZH2, and between EZH2 and RUNX3." (PMID 36476345, 2022).
kidney stones (1 paper, 2024). "IHC analysis of human and mouse kidney tissues confirmed that EZH2 expression levels in kidney stone patients and kidney stone mice were higher than the controls." (PMID 38169402, 2024). "EZH2 knockout in kidney stone mice and EZH2 knockdown in oxalate-stimulated HK-2 cells significantly mitigated the CaOx-induced kidney injury." (PMID 38169402, 2024). "Single-nucleus RNA-sequencing, RNA-sequencing, immunohistochemical and western blotting analyses revealed that EZH2 was upregulated in kidney stone patients, kidney stone mice, and oxalate-stimulated HK-2 cells." (PMID 38169402, 2024). "This study demonstrated that EZH2 was significantly upregulated in kidney stone patients, kidney stone mice, and oxalate-stimulated HK-2 cells." (PMID 38169402, 2024). "To investigate the causes of increased EZH2 in kidney stones, we used UCSC to predict the transcription factors that may regulate EZH2." (PMID 38169402, 2024). "Thus, the expression level of EZH2 is upregulated in kidney stone patients, kidney stone mice, and oxalate-stimulated HK-2 cells." (PMID 38169402, 2024). "Based on the activation of ferroptosis and the upregulation of EZH2 in kidney stones, we hypothesized that EZH2 may modulate CaOx-induced ferroptosis and consequently promote kidney injury." (PMID 38169402, 2024). "Our study sought to explore the function of EZH2 in a kidney stone model." (PMID 38169402, 2024). "Collectively, EZH2 inhibition may exert a protective effect on kidney stones by suppressing ferroptosis." (PMID 38169402, 2024). "However, it is unclear how EZH2 affects ferroptosis in kidney stones." (PMID 38169402, 2024).
Lewis lung carcinoma (1 paper, 2022). "To investigate the biological effect of EZH2 inhibition, we first test whether the dsRNA can be induced in mouse Lewis lung carcinoma (LLC)." (PMID 35912007, 2022).
Listeria infection (1 paper, 2018). "Although both total CD8+- and OVA-specific CD8+ T cells from WT mice increased significantly in response to Listeria infection, little to no expansion of OVA(OVA257-264)-specific CD8+ T cells was observed in Ezh2-c-KO mice." (PMID 29632530, 2018).
luminal B breast carcinoma (1 paper, 2018). A biologic subset of breast carcinoma defined by low to moderate expression of genes characteristic of luminal epithelial cells including estrogen receptor (ER), and high expression of GGH, LAPTM4B, and CCNE1. "In summary, this work establishes an oncogenic function for EZH2 in the development of Luminal B breast cancer and particularly in the metastatic phase of the disease." (PMID 29959321, 2018).
lung neoplasm (1 paper, 2020). A benign or malignant, primary or metastatic neoplasm involving the lungs. "To further examine whether the co-administration of EZH2 inhibitors with gefitinib would inhibit tumor growth in vivo, we established a BALB/c mouse lung neoplasm xenograft model using A549 cells." (PMID 33276757, 2020).
lymphoepithelioma (1 paper, 2023). "High expression of EZH2 was most commonly observed in papillary SCC (5/5, 100%), non-keratinizing SCC (30/40, 75%), basaloid SCC (2/3, 66.6%) while low immunoexpression of EZH2 was predominantly found in keratinizing SCC (5/6, 83.3%) and in lymphoepithelioma-like carcinoma (1/1, 100%)." (PMID 37131568, 2023).
lymphoproliferative disorders (1 paper, 2016). "Upregulation of EZH2 leads to silencing of the genes that are involved in the progression and metastasis of solid tumors, and malignant hematopoiesis and lymphoproliferative disorders." (PMID 27998273, 2016).
male infertility (1 paper, 2025). The inability of the male to effect fertilization of an ovum after a specified period of unprotected intercourse. "Several studies have highlighted the importance of epigenetic regulators, including ARID4B, EZH2, CUL4, and KHDRBS3, in spermatogenesis and their association with male infertility." (PMID 40949795, 2025).
mastocytosis (1 paper, 2012). A clonal myeloproliferative neoplasm characterized by the proliferation and accumulation of neoplastic mast cells in one or multiple organs or organ systems. "Although one patient (patient 22) with SM-AHNMD had UPD7q flanking the region of EZH2, no mutations in EZH2 were found in the cohort of mastocytosis patients." (PMID 22905207, 2012).
medullary thyroid cancer (1 paper, 2025). "These novel findings suggest that EZH2 may serve as a promising therapeutic target in selected patients with medullary thyroid cancer, potentially paving the way for new systemic treatment options with EZH2 inhibitors." (PMID 40075585, 2025).
medullomyoblastoma (1 paper, 2023). "Deletion of either Eed or Ezh2 was therefore sufficient to allow myoid differentiation, reproducing the molecular and histologic features of medullomyoblastoma." (PMID 36635771, 2023).
monoclonal gammopathy of undetermined significance (1 paper, 2017). "EZH2 mRNA expression increases during progression from monoclonal gammopathy of undetermined significance (MGUS) through smoldering MM to overt MM, and high EZH2 mRNA expression in newly-diagnosed MM patients associates with poor outcomes and high-risk clinical features." (PMID 29290968, 2017).
mucinous carcinomas (1 paper, 2016). "Intriguingly, none (0/15) of the specific-type low-grade carcinomas (10 tubular carcinomas, five mucinous carcinomas) had EZH2 overexpression." (PMID 27113214, 2016).
myelodysplastic/myeloproliferative neoplasm (1 paper, 2019). A category of clonal hematopoietic disorders that have both myelodysplastic and myeloproliferative features at the time of initial presentation. "Although loss-of-function mutations in EZH2 primarily result in myelodysplastic/myeloproliferative neoplasms (MDS/MPN), the catalytic activity of EZH2 was also shown to be essential for rapid AML progression." (PMID 31192132, 2019).
myopia (1 paper, 2025).
nasopharyngitis (1 paper, 2014). An inflammatory process that affects the nasopharynx. "We further evaluated the expression level of EZH2 in 47 non-cancer nasopharyngitis biopsy samples and 135 NPC specimens using immunohistochemical staining." (PMID 25237831, 2014). "To further determine whether EZH2 expression was associated with ET-1 in NPC tissues, we examined ET-1 expression in 47 non-cancer nasopharyngitis biopsy samples and 94 NPC specimens using qPCR." (PMID 25237831, 2014).
nephritis (1 paper, 2022). Inflammation of renal tissue. "Inhibiting EZH2 in NZB/NZW F1 lupus mice reduces anti-dsDNA autoantibodies, improves nephritis, and prolongs survival by blocking the IFN-I signaling pathway." (PMID 35795677, 2022).
non-alcoholic steatohepatitis (1 paper, 2025). "In non-alcoholic steatohepatitis-associated HCC (NASH-HCC), YTHDF1 was targeted by lipid nanoparticles (LNPs)-encapsulated small-interfering YTHDF1, which can promote antitumor immunity by suppressing EZH2-IL-6 axis." (PMID 40958857, 2025).
ocular melanoma (1 paper, 2021). A melanoma that arises from the structures of the eye or ocular adnexa. "It is worth noting that all cases of ocular melanoma cases with genetic alteration had copy number deletion of EZH2." (PMID 34381492, 2021). "It is worth noting that all cases of ocular melanoma cases with genetic alteration (<2%) had copy number deletion of EZH2." (PMID 34381492, 2021).
oncocytomas (1 paper, 2021). "EZH2 expression was most commonly seen in papillary cancers (87.0% positive) and least frequent in oncocytomas (63.1%) and chromophobe cancers (64.1%)." (PMID 32303902, 2021).
ovarian serous cystadenocarcinoma (1 paper, 2018). A malignant serous cystic epithelial neoplasm arising from the ovary. "The EZH2 gene also gave a significant P-value with 1.19e-07 in TCGA ovarian serous cystadenocarcinoma." (PMID 29459674, 2018).